RN7SKP17 (RN7SK pseudogene 17)
Gene: Miscellaneous RNA gene on chromosome 14 (76,890,263 to 76,890,613, forward strand). Ensembl gene ENSG00000223174.
Homologues: Orthologues: chimpanzee 7SK (83% identical), mouse Gm56004 (49% identical), guinea pig 7SK (32% identical). Paralogues in human: 7SK (61% identical), RN7SKP180 (60% identical), RN7SKP184 (60% identical), RN7SKP79 (60% identical), RN7SKP240 (59% identical), RN7SKP185 (59% identical), RN7SKP203 (59% identical), RN7SKP30 (59% identical), RN7SKP294 (59% identical), RN7SKP246 (58% identical), RN7SKP249 (58% identical), RN7SKP25 (58% identical), and 283 more.